INS (insulin)
Diseases named in the same sentence as INS in open-access papers (continued):
Sharing a sentence is not in itself a finding about the gene and the disease.
hyperlipidemia (continued). "In the current study supraphysiological increases in circulating GLP1 offer a degree of protection against olanzapine-induced glucose tolerance and lipidemia, in parallel with a reduction in glucagon:insulin." (PMID 36937886, 2023). "It is of note that pregnancy itself is characterized by hyperlipidemia, oxidative stress, and reduced insulin sensitivity." (PMID 37176607, 2023). "- Anti-hyperlipidemia (↓liver weight, ↓liver cholesterol, ↓liver TG, ↓plasma cholesterol). - Insulin sensitizer (↓plasma insulin (male), ↓serum glucose in GTT) in obese Zucker rats (0.75 g/kg of diet, 11 weeks)." (PMID 35769384, 2022). "There is growing evidence demonstrating that adropin enhances insulin sensitivity and lowers hyperlipidemia in obese mice." (PMID 36077198, 2022). "The primary drivers of DSPN pathogenesis are hyperglycemia, hyperlipidemia and impaired insulin signaling, which result in a variety of downstream pathogenic metabolic mechanisms." (PMID 35888162, 2022). "During early hyperlipidemia, when insulin signaling is potentiated, these adaptations boost cardiac utilization and hepatic buffering while further directing excess dietary lipid towards adipocytes." (PMID 36111295, 2022). "Our results indicated that hyperlipidemia in mice is accompanied by changes in insulin regulation and Valine, leucine, and isoleucine biosynthesis." (PMID 36618709, 2022). "Since that review, an increasingly integrated view has been adopted, acknowledging the interplay of other metabolic factors, such as hyperlipidemia and impaired insulin signaling." (PMID 35888162, 2022). "In summary, intestinal permeability correlates with the severity of liver dysfunction, hyperlipidemia, liver fat deposition, insulin resistance, and intestinal barrier damage in patients with NAFLD." (PMID 35685554, 2022). "Adiponectin is associated with antidiabetic and antiatherogenic properties, which mediates insulin-sensitizing effects and reduce hyperlipidemia." (PMID 35548430, 2022). "The present study indicated that crude extracts of B. aurea increase insulin sensitivity and reduce hyperlipidemia in diabetic rats, which rationalizes the traditional medicinal use of this plant as an antidiabetic agent." (PMID 36304231, 2022). "Model 1 was adjusted for sex, model 2 was adjusted for sex, age, and BMI, and model 3 was adjusted for sex, age, BMI, smoking status, past medical history (including DM, HTN, and hyperlipidemia), Chinese herb use, analgesic use, and insulin levels." (PMID 36267905, 2022). "Post-euthanasia, blood plasma was obtained to investigate hyperlipidemia, insulin concentrations, liver, and renal functions." (PMID 35898909, 2022). "Reduced hepatic and muscle glucose uptake resulted in hyperlipidemia due to increased adipose fat mobilization and insulin resistance." (PMID 35567159, 2022). "Organ failure, hypertension, hyperlipidemia, cardiovascular disease, as well as pancreatic oxidative stress, all lead to β-cell destruction and reduced insulin sensitivity." (PMID 35898909, 2022). "Hyperlipidemia, impaired energy expenditure, insulin sensitivity, as well as higher plasma leptin are all shown in the FXN knock-in/knock-out (KIKO) mouse, which mimics T2D-like symptoms." (PMID 35677823, 2022). "In diabetic patients, hyperlipidemia results from the insulin resistance of adipose tissues, leading to lipid abnormalities." (PMID 35160077, 2022). "The results of this study showed that T2DM patients with high age, high BMI, long duration of DM, insulin use, combined hyperlipidaemia, combined DPN, combined DR, combined DKD, high serum FPG, Scr, BUA and BUN levels had a higher prevalence of pruritus." (PMID 35242808, 2022). "We analyze the effects of hyperlipidemia, particularly free fatty acids, on pancreatic beta cells and insulin secretion." (PMID 35884932, 2022).
hyperlipidemia (continued). "A study showed that partial HIF-1A deletion attenuated hypoxia-induced contractions in fasting serum insulin and liver TG levels, thereby mediating the intermittent hypoxia-induced hyperlipidemia response." (PMID 35722157, 2022). "The metabolic dysfunctions in cancer (described in detail in Section 3.1, Section 3.2, Section 3.3, Section 3.4 and Section 3.5) include reduced insulin sensitivity, hyperlipidemia, impaired mitochondrial function, chronic inflammation, and cancer cachexia." (PMID 33801684, 2021). "The researchers also showed that consuming 9 g of oat bran improves glycemic response, insulin and lipidemia." (PMID 33849494, 2021). "SJP supplementation reduced the fasting glucose (p < 0.05) and fasting insulin (p < 0.05) levels and ameliorated serum hyperlipidemia with a reduction in the levels of TC (p < 0.05), TG (p < 0.05), and LDLC (p < 0.05) in HFD-fed mice." (PMID 35237590, 2021). "Exercise potently improves insulin sensitivity, hyperlipidemia, mitochondrial function, inflammation, muscle mass, and strength." (PMID 33801684, 2021). "Exercise produces acute as well as longer-term metabolic benefits by improving insulin sensitivity, restoring hyperlipidemia, reducing inflammation, enhancing mitochondrial function, and increasing muscle mass and strength." (PMID 33801684, 2021). "The intervention of Y, PVE, and YPVE decreased blood glucose, insulin, hyperlipidemia, and inflammatory cytokine levels in mice fed with HFD." (PMID 34712684, 2021). "• Suppressing hyperlipidemia;• Suppressing oxidative stress;• Enhancing insulin sensitivity;• Regulating intestinal barrier function;• Suppressing TLR4-related inflammation response;• Enhancing autophagy;• Suppressing cell apoptosis." (PMID 34414181, 2021). "Deficiencies in lipolysis lead to increased intracellular lipid accumulation, resulting in abnormal cellular physiology, hyperlipidemia, and insulin resistance." (PMID 34812408, 2021). "Implementing a time-restricted feeding schedule decreases body fat, fasting glucose and insulin levels, insulin resistance, hyperlipidemia, and inflammation in humans." (PMID 34001884, 2021). "Here we report that the FXN knock-in/knock-out (KIKO) mouse shows hyperlipidemia, reduced energy expenditure and insulin sensitivity, and elevated plasma leptin, recapitulating T2D-like signatures." (PMID 31974344, 2020). "Alternatively, when hyperlipidemia and the use of insulin and OHAs were included as independent variables in the models and HDL-C, LDL-C, and triglycerides were excluded, plasma S1P levels were still associated with CAN in women." (PMID 32728147, 2020). "Since hyperlipidemia-induced ROS production in skeletal muscle is involved in inhibition of insulin action, we evaluated the mRNA level of markers of oxidative stress and antioxidant defence mechanism in this tissue as well as in epididymal adipose tissue." (PMID 33344504, 2020). "Previous research showed that taurine was able to improve insulin sensitivity and hyperlipidemia because taurine is required for bile acid conjugation, which is lost in the excreta, and then the level of taurine will be decreased." (PMID 32410994, 2020). "On the other hand, hepatic hypertrophy and hyperlipidemia were observed in both obese rats, and concomitantly, serum leptin and insulin were higher in fatty rats than in lean rats." (PMID 32041091, 2020). "This increases insulin secretion and consequently activates hepatic lipogenesis and cholesterol excretion, leading to disturbances in lipid metabolism (evidenced by hyperlipidemia)." (PMID 33396905, 2020). "Future clinical studies are needed to test the effectiveness of (R)-(−)-carvone in treating hyperlipidaemia and to test its effects on insulin release in humans." (PMID 33447133, 2020). "This increases insulin secretion and consequently activates hepatic lipogenesis and cholesterol excretion, leading to hyperlipidemia." (PMID 33158191, 2020).
hyperlipidemia (continued). "A study using human APOE2 and APOE3 gene replacement mice showed that APOE2 mice had elevated fasting plasma triglyceride and insulin levels and displayed prolonged postprandial hyperlipidemia." (PMID 31485353, 2019). "Similar trends were observed in the levels of free fatty acids, another index of hyperlipidemia, as well as in the levels of blood glucose and insulin." (PMID 31920693, 2019). "Selenate supplementation mitigated hyperlipidemia and slightly decreased the levels of insulin and HbA1c induced by HFD, suggesting a protective role of selenate on HFD-induced dysregulation of lipid metabolism." (PMID 31822702, 2019). "Ces1g is a direct target of FXR, and FXR activation is known to improve insulin sensitivity, and has protective effects against hyperlipidemia and NAFLD." (PMID 28677105, 2018). "We previously reported that BAIBA treatment reversed hyperlipidemia-induced inhibition of insulin signaling in both differentiated C2C12 cells and mouse skeletal muscle." (PMID 29592806, 2018). "Among the diabetic patients, predictors for 10 years’ mortality were higher on EuroSCORE (HR 1.37 95% CI 1.3–1.45, p < 0.001), hyperlipidemia (HR 1.45 95% CI 1.06–1.97, p = 0.021) and insulin treatment (HR 2.11 95% CI 1.34–3.3, p = 0.001)." (PMID 30497472, 2018). "Since high rates of carbohydrate and fat consumption increase insulin resistance and oxidative stress, improving insulin signalling can be achieved by decreasing the intake of carbohydrates and lipids, and attenuating the postprandial hyperlipidemia." (PMID 28718838, 2017). "Increased secretion of insulin will enhance lipogenesis and inhibit lipolysis leading to amelioration of hyperlipidemia." (PMID 26927161, 2016). "We adopted highly purified EPA ethyl ester, which was approved by Japan’s Ministry of Health, Labour and Welfare for the treatment of peripheral artery disease and hyperlipidemia, to examine its effects on postprandial glucose and insulin metabolism." (PMID 27565734, 2016). "The proportions of hyperlipidemia and insulin application were higher in DR group than that in DM controls (P = 0.042 and P < 0.001, resp)." (PMID 26989329, 2016). "A model based on clinical data including age, gender, hyperlipidemia, plasma creatinine and treatment with insulin was improved by HbA1c and E/E′ ratio." (PMID 26842466, 2016). "Patients with depressive symptoms were significantly more likely to be female, to have a smoking habit, to be diagnosed with hyperlipidemia, neuropathy and treated with insulin (test χ2)." (PMID 26613755, 2016). "Those conditions manifest themselves as hyperlipidemia, believed to be a major preceding event in the development of skeletal muscle insulin resistance." (PMID 26380311, 2015). "The elevated insulin acts primarily on the liver and adipose tissue and results in hyperlipidemia and elevated free radical production and a shift in nutrient storage from glycogen to fat." (PMID 25569521, 2015). "PPARγ is also a drug target and, currently, its synthetic ligands are used to treat hyperlipidemia and as insulin-sensitizing antidiabetic agents." (PMID 24790595, 2014). "Differential gene expression of Adipocytokine Signaling Pathway in omental relative to subcutaneous adipose tissue in normal pregnancy suggests a pattern of insulin resistance, hyperlipidemia, and inflammation." (PMID 26029481, 2013). "Nuciferine is a major active aporphine alkaloid from the leaves of N. nucifera Gaertn that possesses anti-hyperlipidemia, anti-hypotensive, anti-arrhythmic, and insulin secretagogue activities." (PMID 23691094, 2013).
hyperlipidemia (continued). "PPAR-α and PPAR-γ are mainly involved in regulating lipid metabolism, insulin sensitivity, and glucose homeostasis, and their agonists are used in the treatment of hyperlipidemia and T2DM." (PMID 23781121, 2013). "In conclusion, prior exercise does not appear to ameliorate the effects of a high-fat meal on increases in VEGF, PlGF, or bFGF despite improving insulin sensitivity and reducing lipemia." (PMID 24303126, 2013). "At the time of diagnosis, the patient was a diabetic on insulin and had marked hyperlipidaemia, which were attributed to long-term antiretroviral combination therapy." (PMID 23762710, 2013). "Combination of MET with GSP showed effective improvement in insulin sensitivity and better reduction in hyperlipidemia compared to MET alone." (PMID 24307947, 2013). "HFD leads to vast upregulation of A2bAR in the liver and elimination of A2bAR results in hyperlipidemia, while the latter has been shown to acutely trigger ß-cells to hyper-secrete insulin." (PMID 22848385, 2012). "In clinical practice, PPARα agonists (fibrates) are used to treat hyperlipidemia, whereas PPARγ agonists (TZDs) are used to increase insulin sensitivity in muscle and adipose tissue." (PMID 20811644, 2010). "Diminished hepatic and muscular uptake of glucose produced hyperlipidemia due to increased fat mobilization from adipose tissue and resistance to the antilipolytic actions of insulin." (PMID 19835614, 2009). "Animal experiments have indicated that a high-fat diet, combined with ten weeks of blue light exposure, could result in greater body weight, hyperlipidemia, and reduced insulin sensitivity compared to the control group, leading to metabolic abnormalities." (PMID 41515280, 2026). "In addition, DHA supplementation significantly elevated insulin levels in overweight men with hyperlipidemia." (PMID 40292545, 2025). "Additionally, they developed hyperlipidaemia, higher hepatic lipid content, as well as elevated fasting blood glucose and insulin levels." (PMID 40256914, 2025). "Additionally, probiotic supplementation has been shown to improve fasting blood glucose levels, insulin sensitivity, and hyperlipidemia." (PMID 39456659, 2024). "In multivariate analysis, postpartum T2DM was associated with SAV, GDM (with/without insulin), nulliparity, pre-pregnancy BMI, chronic hypertension, hyperlipidemia, and DM family history." (PMID 38514819, 2024). "It was reported that the administration of UroA to high-fat diet-fed mice increased energy expenditure and prevented hyperlipidemia by enhancing thermogenesis in brown adipose tissue and inducing the browning of white adipose tissue, decreasing insulin resistance." (PMID 38392186, 2024). "Non-insulin-based indicators of IR may be co-linear with hyperlipidemia, DM and other indicators in multivariate Cox models, leading to biased results of statistical analysis." (PMID 38419016, 2024). "It is widely believed that EPA and DHA regulate energy metabolism, and have advantages on anti-inflammation, promoting insulin secretion, and enhancing peripheral insulin sensitivity, resulting in reduced risk of a variety of metabolic diseases such as CVD, T2D, hyperlipidemia, and even cancer." (PMID 38501107, 2024). "There were twenty studies looking at fenugreek, mainly for its impact on blood glucose, insulin and lipids, in healthy individuals, diabetics, individuals with coronary artery disease and adults with hyperlipidaemia/hypercholesterolaemia." (PMID 38068725, 2023). "Fair evidence indicates that Wnt/β-catenin signalling favours improved insulin/glucose and lipid homeostasis and that antagonism of this pathway by oxidative stress may contribute to IR and hyperlipidaemia." (PMID 36698149, 2023). "Indeed, metabolic and oxidative stress is the main cause of hormonal malfunction in patients with T2DM, and on the other hand, persistent hyperlipidemia gradually shifts an insulin response to the degree of insulin insensitivity." (PMID 37604307, 2023).
hyperlipidemia (continued). "Acquired hyperlipidemia comes from an unbalanced diet or insulin resistance." (PMID 35054478, 2022). "Increased serum AST levels in obese organisms may be associated with non-alcoholic fatty liver disease and may result from a combination of hyperlipidemia, insulin deregulation and reduced antioxidant levels." (PMID 35327129, 2022). "However, in mid and late pregnancy, insulin leads to an intensification of lipolysis of fatty deposits, leading to maternal hyperlipidemia, specifically due to hypertriglyceridemia and FFA, to provide energy for the growing fetus." (PMID 35631313, 2022). "A comparison of the information collected from DP patients and those with T2DM alone showed statistically significant differences in age, BMI, duration of DM, insulin use, combined hyperlipidaemia, combined DPN, combined DR, combined DKD, and serum levels of FPG, Scr, BUA and BUN (P < 0.05)." (PMID 35242808, 2022). "A water-soluble extract of the leaves of G. sylvestre lowered insulin requirements, improved blood glucose homeostasis, better controlled hyperlipidemia, reduced serum amylase activity, and boosted b-cell activities in insulin-dependent patients after extended dosing." (PMID 35268815, 2022). "This may be because people with T2DM have an increased number of risk factors, despite the fact that glycemic medications can also target hyperlipidemia and impair insulin signaling pathways." (PMID 35888162, 2022). "Thus, adipocyte and macrophage O-GlcNAc responses to prolonged hyperlipidemia, despite their opposite directions, likely both contribute to adipose tissue insulin resistance and the dysregulation of lipolysis in obese individuals." (PMID 36111295, 2022). "Owing to the impaired secretory function of the patient’s pancreatic islets, liver dysfunction, hypothyroidism, severe hyperlipidemia, and huge hepatic adenoma, we adopted diet control, insulin therapy, and hepatic adenoma resection to alleviate this situation." (PMID 36167523, 2022). "In addition, factors such as cell type, energy status, insulin signaling, lipid species and duration appear important in shaping unique relationships between hyperlipidemia and the O-GlcNAc regulatory system." (PMID 36111295, 2022). "In vivo, this may be restricted to the context of hyperlipidemia as numerous adipocyte OGT models fail to impact insulin sensitivity in standard chow fed mice." (PMID 36111295, 2022). "Findings from the studies suggest that a lack of adiponectin in insulin-deficient mice aggravates insulin-mediated lipoatrophy and hyperlipidemia to lethal levels." (PMID 33902691, 2021). "From the enrichment results, lipid metabolism and insulin resistance processes presented a strong connection with the potential regulation effect of HTJZD in treating hyperlipidemia, which may shed light on the exploration of the efficacy of HTJZD." (PMID 33936248, 2021). "Insulin therapy for the treatment of hyperlipidemias is still a subject of scientific debates." (PMID 34947937, 2021). "However, normal GSIS results on isolated islets led them to conclude that their insulin secretion defect was secondary to their hyperlipidemia phenotype." (PMID 34440212, 2021). "Hyperlipidemia during pregnancy is a physiological phenomenon which occurs as a result of increased insulin resistance and the synthesis of lipoproteins and lipolysis in adipose tissue, in order to provide fats as a source of energy for the development of the fetus." (PMID 31807722, 2019). "In detail, CDK5 tv1 levels correlated positively with serum insulin (μU/ml) and glycated haemoglobin (HbA1c; % or mmol/mol) levels and negatively with hyperlipidemia in T2D patients, while positively with serum triglycerides levels (mg/dl) (p < 0.05) in CTRF+ subjects." (PMID 30728419, 2019). "In our study, the reduced effect of glycine on GPX1 and the increased activities of CAT and Cu/Zn-SOD may be related to enhanced insulin signaling and sensitivity and reduced fat accumulation and hyperlipidemia." (PMID 29675131, 2018).